C3 (complement C3)
Diseases named in the same sentence as C3 in open-access papers (continued):
Sharing a sentence is not in itself a finding about the gene and the disease.
infection (continued). "The score incorporates immune (C3 level, IgG level, CD4+ T-cell count, CD8+ T-cell count), and clinical (recipient age, glomerular filtration rate, recipient age, and infection within the first month) variables." (PMID 39660122, 2024). "On the other hand, the increased levels of C3, IL-6, IL-12, TNFα and CXCL1 as a means of activation of innate-mediated response in early infection phases have been found in SARS-CoV-2-infected Caco-2 cells." (PMID 38886736, 2024). "In each individual infection, MASP stimulation of the fission of C3 into C3a and C3b was programmed to increase C3a formation by four orders of magnitude at the exponential rate of an order of magnitude (10-fold) increase every two days." (PMID 38234438, 2024). "This may have been correlated with the elevation of nonspecific immune parameters, such as phagocytic activity, lysozyme, NO, C3, and antioxidant enzyme activities, in addition to the reduced levels of glucose and cortisol, which could have strengthened the defense of fish against infection." (PMID 36830534, 2023). "As speculated, immediately after infection (5 min post-infection), neutrophils (Ly6G+Ly6CInt), eosinophils (Ly6G+Ly6Clow), and monocytes (Ly6G-Ly6Clow and Ly6G-Ly6Chi) from WT mice engulfed a significantly higher number of conidia compared to that from C3-/- mice." (PMID 36211424, 2022). "Therefore, it appears that C3 might also be involved in antibacterial defence and thereby relevant for opsonization and chemotaxis to attract macrophages and granulocytes to the site of infection." (PMID 34767613, 2021). "Changes in gene expression in the brains of infected animals is minimal at 2- and 4-days post infection with moderate increases in Interferon-inducible CXCL10, CXCL11, B2m, and STAT1, as well as pro-inflammatory TNF, IL-1b and C3." (PMID 32133008, 2020). "Other genes, including PAL1, C4H, 4CL1, HCT, C3′H, COMT1, and CAD5, were strongly activated upon Pst DC3000 (AvrRpm1) infection and MYB15-dependent." (PMID 33042196, 2020). "However, a recent study found that Factor X was required to promote adenovirus infection in C4-competent as well as C3-deficient mice, suggesting the presence of an unknown C4-dependent mechanism that blocks infection of non-enveloped viruses." (PMID 30926239, 2019). "Our KEGG pathway enrichment analysis indicates that the up-regulated DEGs including C3, PLG, CFD, CR1, and C1QB are still enriched in complement and coagulation cascades, up to 24 h after infection." (PMID 31316336, 2019). "By contrast, there was a trend toward reduced amounts of C3 upon infection with WT-PAO1, strongly suggesting that the presence of LasB in WT-PAO1 was responsible for degrading the PAMPs-induced secretion of C3." (PMID 30083156, 2018). "In the same supernatants used for the Proteomics analysis, we showed that Control AMs produced considerable amounts of C3 (1,000 ng/mL levels), and that ΔLasB-PAO1 infection upregulated that production, presumably through PAMPs stimulation of AM receptors." (PMID 30083156, 2018). "While studying infections of human MDM with F. tularensis SCHU S4, we observed that large numbers of macrophages in infected cultures died by 24 h PI and that cell death was C3-dependent." (PMID 29312899, 2017). "We postulate that exacerbation of infection in tg mice infected with GAS strains that bound complement inhibitors, resulted in impaired opsonization with mouse C3 fragments." (PMID 26200783, 2015). "In addition, during the first week of infection, the absence of C3 was associated with partial protection characterized by reduced weight loss, better clinical score and lower bacterial burden, which might be explained by a different mechanism." (PMID 23189195, 2012). "Three days after oral infection of adult zebrafish with Aeromonas hydrophila harboring pRAS1, elevated expression of pro-inflammatory cytokine (TNF α, IL-1β and IL-8) and complement C3 genes in the intestine coincided with disease symptoms." (PMID 22429905, 2012).
infection (continued). "Examination of the ontologies enriched in this set of up-regulated genes showed genes known to play a role in infection processes, including NR3C1, PTPRC, SFRS1, SFRS5, SMAD3, C3 and DDX58." (PMID 22363497, 2012). "All these results indicated that, in addition to C3, EF-Tu was important for LVS infection of THP-1 cells through nucleolin." (PMID 18789156, 2008). "This state is supported by a partial impairment of mice lacking C3 or C3 receptors in bacterial clearance at the relatively lower level of infection." (PMID 41214213, 2025). "This study demonstrates that during LIC infection, the absence of C3 does not impact mouse survival but results in increased renal leptospiral load and fibrosis." (PMID 41251377, 2025). "In our patient, the constellation of dyspnoea, pleuritic pain, hypoxia, and bilateral ground-glass opacities on CTPA, together with low procalcitonin (0.07 μg/L), normal complement levels (C3: 1.29 g/L, C4: 0.47 g/L), and mildly raised CRP (23 mg/L), favored ALP over infection." (PMID 41287713, 2025). "In particular, we observed lower average C3 level in children with severe infection than in those with non-severe infection." (PMID 41291834, 2025). "Western blot experiments further confirmed that infection with live S. aureus stimuli led to the upregulation of C3 in BV2 cells, whereas heat-killed S. aureus did not have any effects." (PMID 40008883, 2025). "In this study, we show that cells lacking C3 exhibit altered gene expression that influences immune responses to infection and inflammation." (PMID 41441980, 2025). "C3 KO mice had similar bacterial burdens compared to WT B6 mice and had delayed clearance of an NMII infection, indicating that C3 is not necessary but contributes to bacterial clearance." (PMID 40586810, 2025). "Our results show that approximately half of the VECs analyzed were positive for C3 (49.8%), with a non-significant increase after infection with either the Colonizing (63.2%) or VVC (63.8%) strain." (PMID 40985395, 2025). "When a similar infection experiment was conducted using the same trypanosome cell line to infect mice lacking complement C3, then the first wave of infection was no longer controlled." (PMID 38655765, 2024). "Although an increase in C3 mRNA levels was also observed on the 10th post-infection day in comparison to the healthy control groups, no statistically significant result was obtained (p > 0.05)." (PMID 39766497, 2024). "(2014) described a composite “immunological score” using immunoglobulins (IgG, IgM, IgA), complements (C3, C4), and lymphocyte subsets (CD3+, CD4+, CD8+ T cells, NK cells, and B-cells) correlating with severe infections in a cohort of heart transplant recipients." (PMID 39660122, 2024). "Finally, an experimental study showed that a primary infection of Carassius auratus by Dactylogyrus intermedius induced the down-regulation of two immune-related factors (TGF beta and C3)." (PMID 39080784, 2024). "Under normal conditions, C3–/– mice do not present any specific phenotype, but exhibit increased mortality after infection by group B streptococci." (PMID 38912583, 2024). "Its role in promoting opsonization by phagocytic cells is well documented, but our findings demonstrated that the C3 deposition impacted the infection of non-phagocytic (e.g., A549) cells by internalized S. aureus." (PMID 39310788, 2024). "Moreover, the expression of immune-related genes (SAA, iNOS, IL-1 β, IL-6, IL-10, TNF α, C3, MHC I, MHC II, CD4, CD8, TCR α, IgM, IgD and IgZ) increased in all groups post infection, which was more significant in the vaccinated groups." (PMID 36969197, 2023). "C3, a non-specific immune factor, can protect aquatic animals from pathological infection when it is activated." (PMID 36830467, 2023).
infection (continued). "In contrast, our previous study has revealed that Df, a well-known complement enhancer in the AP by cleaving Bf to promote the cleavage of C3 and the production of C3b, is observed with a continued up-regulated expression in the grass carp during GCRV infection, even at the late stage of infection." (PMID 36232671, 2022). "In teleost, expression pattern of C3 was determined in various tissues with or without pathogen infection, and C3 transcripts was significantly impacted by environment stress (pH and temperature) in tissues." (PMID 35281048, 2022). "Building on these findings, Kohn and colleagues elegantly demonstrated that early depletion of serum-C3, via intravenous treatment with cobra venom factor (CVF) 2 days before infection in WT mice, increased disease severity and decreased recovery time, compared to mock-treated mice." (PMID 35925892, 2022). "Without smoothing, GO terms related to digestion as well as infection and autoimmune-related pathways and complement cascade components (C3, C5) were identified." (PMID 35380614, 2022). "At a high (1x107) dose, both WT and C3-/- mice failed to survive; however, in the C3-/- mice group, 100% death occurred on the 5th day post-infection (dpi) compared to the 7th dpi in WT mice group." (PMID 36211424, 2022). "The IL-6 levels also increased with the time of infection but did not vary between WT and complement knockout (C3-/- and C5aR1-/-) mice groups." (PMID 36211424, 2022). "Furthermore, dietary 30, 60, 120 mg/kg Zn–Met supplementation noticeably increased the thymus index at 2 days post-infection (2 DPI) and 8 DPI (p < 0.05), and 120 mg/kg Zn–Met enhanced the serum IgA at 2 DPI and IgA, IgG, IgM, C3 at 8 DPI (p < 0.05)." (PMID 35602082, 2022). "However, what was striking was the lower abundancy of proteins involved in response to infection (ISG15, NME2, IFNγ, and C3)." (PMID 34962717, 2021). "C3-/- mice showed mortality comparable to that of wild-type mice (P = 0.9), suggesting that complement does not play a major role in this infection." (PMID 34093560, 2021). "Proteomic analysis of mass spectrometry data from A549-ACE2 cells infected, or not, with SARS-CoV-2 confirmed the increased production of C3 protein following infection, consistent with the observed transcriptomic data." (PMID 33827897, 2021). "Although early graft dysfunction may cause low C3 ratio through the reduced production of complement, the results of our logistic regression analysis suggested that immunological mechanisms of hypocomplementemia other than early graft dysfunction and infection by day 7 underlie in non-survivors." (PMID 34349754, 2021). "To test how the absence of TNF would affect C3 production during S. Tm infection, we infected TNFa−/− mice and heterozygous littermate controls with S. Tm." (PMID 34529751, 2021). "In addition, the expression of c1ql2, C3, C5, C7, C9, CFB, and complement factor H (CFH) was regulated in rainbow trout stimulated with β-glucan upon infection with A. salmonicida, suggesting improved immune enhancement." (PMID 34835165, 2021). "The results presented in the current study provide evidence that genetic variants in regulatory regions (cis-eQTLs) can up-regulate the C3, S100B, and SELENOS gene expression which might activate a prompt resolution of the infection." (PMID 33432064, 2021). "Of note, other cells with a damaged nucleus were not stained with C3A antibody and were either stained or not with dsRNA antibody, suggesting the existence of a C3-independent death that can be due to both direct and indirect infection." (PMID 34835061, 2021). "In contrast, no major change in serum complement C3 levels was observed during the course of infection." (PMID 32613944, 2020). "We speculated that infection with SARS-CoV-2 somehow activated the alternate pathway in the complement system first, and thus consumed a large amount of C3." (PMID 32713370, 2020).
infection (continued). "Such an escape relies on the ability of S. flexneri to shed the C3 factor with a majority of bacterial cells being C3-negative four hours after infection." (PMID 32274388, 2020). "Our retrospective analysis was limited by missing data, as some of the recorded infections lacked corresponding C3 levels in the preceding 30 days and no leukocyte counts were collected." (PMID 32972440, 2020). "Capsid-deposited C4b neutralizes infection independent of C2 and C3 but requires C1q antibody engagement." (PMID 30926239, 2019). "Immunofluorescence staining of blood smears indicated that meningococci are indeed efficiently opsonized with C3b during infection in WT mice and in Hc°/° mice, whereas no opsonization occurred in C3−/− mice." (PMID 29362231, 2018). "First, it was retrospective in nature, and only some of the identified patients with or without infection were subjected to the measurement of T cell subsets, anti-dsDNA, complement C3, complement C4, IgG, and globulin." (PMID 29267496, 2017). "The C3d/C3 ratio at admission was on average twice as high in aHUS patients than in infection-induced HUS patients; this was not a statistically significant difference, and was most probably due to the low number of patients." (PMID 27718086, 2017). "Treatment with human factor H did not attenuate disease scores, serum pro-inflammatory cytokines, or vascular permeability and did not significantly affect C3 and C3a production at 26 h post-infection." (PMID 26872035, 2016). "Several strains of mutant C57BL/6 mice (TCR-/-, C3-/-, CD16-/-, MyD88-/-, TRIF-/-, INFγ-/-, TNFR1-/-, Gal3-/-, Prf1-/-) with defects in innate and adaptive immunity were examined for expression of this infection-induced, immunosuppressive trait." (PMID 27403737, 2016). "At 2 hours after infection, C3 values were not significantly different, but at 24 hours after infection, insulin-rescued rats demonstrated a 1.7-fold increase compared with diabetic rats (P = 0.01)." (PMID 25610878, 2014). "Consistent with the flow cytometry data, at 2 hours after infection, a trend towards increased C3-fragment opsonization was noted for euglycemic rats compared with diabetic rats (P = 0.06)." (PMID 25610878, 2014). "Our data show there are low concentrations of IgG, C4, and C3 present in peritoneal fluid in the absence of infection." (PMID 25610878, 2014). "Overall, our results indicate an intracellular pathway of C3 activation that in T cells is catalyzed by CTSL and occupies a central niche in basal cellular homeostasis and in immunological T cell effector function during infection." (PMID 24315997, 2013). "Virus from such an early infection period would be perfect to test for C3-deposition in the absence of virus-specific IgG and to show that the HCV envelope proteins E1 and E2 can directly activate the complement." (PMID 23049856, 2012). "To estimate the remaining 71 kinetic parameters, we generated test data by incubating human blood under normal and infection-inflammation conditions with beads coated with PC or GlcNAc followed by immunodetection of the deposited CRP, C4, C3 and C4BP in time series." (PMID 21283780, 2011). "Since C3-deposition is the pivotal step towards the formation of the MAC, we sought to detect C3 deposition on the bacteria by incubating P. aeruginosa with whole serum, or serum depleted of CRP or ficolin in the healthy or infection-inflammation conditions." (PMID 19180241, 2009). "During the chronic phase of infection, sera of all vaccinated macaques induced C3 activation and opsonisation on SIV, independent of the viral load." (PMID 19545395, 2009). "In this study, the non-canonical roles of C3 in infection and inflammation were investigated." (PMID 41441980, 2025).
infection (continued). "Notably, all of the tested C3−/− mice succumbed to the infection with 103 CFU of Spn6A, an otherwise nonlethal dose (right)." (PMID 40073120, 2025). "Thus, C3, but not C4 is required for Kpn opsonophagocytosis by inducing C3b deposition as well as by supporting phagocyte recruitment to the intestine following infection." (PMID 41279015, 2025). "Furthermore, when the C3 mRNA levels of all the groups (post-infection days 10, 20 and 30) were compared among themselves, no statistically significant result was detected (p > 0.05)." (PMID 39766497, 2024). "Additionally, we discovered that only C3 protein deposited on bacterial surfaces can enhance autophagy during infection as C3 transfected in the absence of bacteria failed to do so." (PMID 39310788, 2024). "Consequently the complement pathway functioning changes by increased expression of genes C2, C3, C4, CD55, and factor H, which may be needed as an early defence mechanism against dysbiosis/infection or a dysfunctional barrier." (PMID 37789352, 2023). "Although the WT mice sera could not rescue the infected mice from lethal infection, it prolonged survival compared to C3-/- mice sera." (PMID 36211424, 2022). "The complement factors C3, C9, and CFHR3 (complement factor H-related protein 3 precursors) were down-regulated with the wt isolate, which could be related to an attempt of the virus to regulate the inflammatory response during infection." (PMID 35215144, 2022). "In contrast, mice lacking C3 did not control the infection and parasite burden remained high." (PMID 36038546, 2022). "To investigate whether complement C3 is necessary for control of parasite burden in the first wave of infection, we infected mice lacking C3 with ISG65+/+ or ISG65−/− trypanosomes." (PMID 36038546, 2022). "Additionally, late depletion of serum-C3 (6d p.i.)did not affect infection outcome, suggesting that C3 and its bioactive forms C3a and C3b, are working to enhance early innate immune function." (PMID 35925892, 2022). "Utility of serum leakage against secondary infection may not be limited to iron nutritional immunity as other immune factors were delivered, for example complement c3 which has well-established anti-microbial functions." (PMID 35967332, 2022). "Mechanisms known to promote C4 consumption such as infection may play a role at the beginning of the disease but are not continuously present in the patients, whereas intrinsic C3 activation drivers are (C3NeFs, C4NeFs, and in some cases genetic changes)." (PMID 34456924, 2021). "Moreover, C3, C5, C2, C1S, C4BPA (genes involved in the complement pathway) and SERPING1 (a regulator of complement activation) were significantly up-regulated, indicating an important role of the complement pathway in this infection." (PMID 34203742, 2021). "To test whether C3 degradation had any influence on the capacity of P. aeruginosa to grow in human serum, where the complement system is the main effector, we evaluated the viability of PA14 and the isogenic mutants in an ex vivo serum model of infection." (PMID 35145924, 2021). "The analysis of the mRNA profiles showed that, while C3 and cxcr4a mRNA levels did not change throughout the experiment, ccr6a, akr2, and IL-1β levels increased after vaccination with α-Gal and remained unchanged after infection." (PMID 32344637, 2020). "The presence of C3 at the onset of infection did not modulate bacterial adhesion." (PMID 28676846, 2017). "Likewise, infection with C3-opsonized SCHU S4 ΔfevR alone also did not induce macrophage death, whereas C3-opsonized wild type SCHU S4 alone did." (PMID 29312899, 2017). "Importantly, when depletion of lung CD103+ DCs in langerin-DTR mice was followed by infection with PR8-OT-I, priming of OT-I CD8+ T cells in the dLN was severely reduced when compared with PR8-OT-I infected WT, similar to our observations in the C3−/− mice." (PMID 23326231, 2013).